WNT1 (Wnt family member 1)
Diseases named in the same sentence as WNT1 in open-access papers (continued):
Sharing a sentence is not in itself a finding about the gene and the disease.
tumor (continued). "Represented by IL-1 and IL-6, primary mediators of GBM tumor cells in the inflammatory TME can orchestrate immunological activation and inflammatory signaling cascades such as hypoxia-inducible factor-1α (HIF-1α), Wnt-1, nuclear factor-kappa B (NF-κB), and STAT3 in GBM." (PMID 35572545, 2022). "Additionally, Wnt-1, β-catenin, cyclin-D1, MMP2, and MMP9 as well as Ki-67 levels were higher in tumor cells of the model + sh-SOST group than that of the model + sh-NC group, demonstrating that SOST suppression was capable of activating Wnt/β-catenin signaling in ocular orthotopic tumor models." (PMID 35785219, 2022). "Together, these data suggest that dormant residual disease in the HER2/neu model may be enriched for tumor cells that have undergone epithelial-to-mesenchymal transition (EMT), whereas dormant residual disease in the Wnt1 model may be enriched for tumor cells with a basal epithelial phenotype." (PMID 34088357, 2021). "In parallel, SOX2 was found to cooperate with important oncogenes, like Wnt1 (OMIM: 164820), Wnt2 (OMIM: 147870), c‐Myc (OMIM: 190080), and Notch1 (OMIM: 190198), to promote lung tumor occurrence, while downregulation of SOX2 inhibited proliferation and induced apoptosis in tumor cells." (PMID 32130794, 2020). "A global transcriptomic comparison of these FACS populations using a principal component (PC) analysis highlights that the first PC separates the Cd49fpos/Epcamneg population from the Cd49fpos/Epcampos population, irrespective of the Wnt1 tumor class from which they were derived." (PMID 31213486, 2019). "It is worth noting that the expression of two additional genes tested but not shown, Wnt1 and Wnt10b, was detectable in the mouse tumor tissues, but was below the limit of detection in the controls; thus, while the relative analysis was not possible, these genes were also up‐regulated." (PMID 26778414, 2016). "However, tumor vasculature and factors that can contribute to vascularization have not been clearly described for the Wnt1 tumors." (PMID 20087418, 2010). "Similarly, Brca1 and Brca2 heterozygosity did not affect tumor formation induced by the Wnt-1 transgene, and partial deletion of the INK4a locus that encodes both p16INK4a and p19ARF did not result in increased DMBA-induced tumor formation." (PMID 19267898, 2009). "The ability of the anti-Wnt-1 antibody to down-regulate the expression of downstream targets of Wnt/β-catenin signaling, including c-Myc, cyclin D1, and survivin, suggest that a broad spectrum of cellular mechanisms can be triggered in concert to halt HCC tumor growth." (PMID 19778454, 2009). "A previous study demonstrated the expansion of a K6 expressing population of cells in tumours that are induced by components of the Wnt/β-catenin signalling pathway, including Wnt1, c-Myc and β-catenin, yet not in tumours induced by other oncogenes such as neu, PyVmT and Ras." (PMID 19344510, 2009). "Contrary to our hypothesis, we found that the adoptive transfer of Rapamycin-resistant T1 cells did not suppress Wnt-1 tumor growth or increase the therapeutic efficacy of Rapamycin." (PMID 18570671, 2008). "To investigate whether the synergy between the AR and Wnt transcriptional activities would lead to accelerated tumor cell growth, we set out to measure the growth of PC3 cells under the conditions of overexpressing the AR alone, Wnt1 alone, or the combination of both." (PMID 18218096, 2008). "In our study, Wnt-1 tumors grew slower in non-irradiated mice than in irradiated, BM reconstituted animals, suggesting that host immunity may contribute to tumor progression." (PMID 18570671, 2008). "However, Myc-and Wnt1-induced neoplasms are independent of cyclin D1, whereas Hras-and Neu-induced carcinomas are dependent on cyclin D1, indicating that tumor phenotype and tumor genotype are not consistently matched." (PMID 15535849, 2004).
tumor (continued). "Finally, expression profiles of residual tumor cells from HER2/neu and Wnt1 GEM models are strikingly similar to each other, suggesting that residual tumor cell biology reflects conserved properties and is not specific to the specific oncogenic pathway that induced the tumor." (PMID 34088357, 2021). "Cell lines expressing control non-targeting shRNA and Wnt1 shRNA were injected intravenously or orthotopically into the mammary fat pads of female BALB/c mice, which were monitored for tumor metastasis." (PMID 26202299, 2015). "Transgenic mice that overexpress COX2 and Wnt1 each alone do not produce tumor, but cross the two components to generate K19-Wnt1/C2mE mice, which express both COX2 and Wnt1, induce cancer in these mice." (PMID 23217022, 2012). "To examine the effect of dominant negative PEA3 on Wnt1-driven tumorigenesis, we compared tumor latency in MMTV/Wnt1 and bigenic MMTV/Wnt1, MMTV/ΔNPEA3En virgin females, generated by interbreeding MMTV/Wnt1 mice with MMTV/ΔNPEA3En animals." (PMID 20107508, 2010). "We did not detect significant differences in tumor incidence and growth between SAFB1+/+/Wnt-1 and SAFB1+/-/Wnt-1 mice, and between DMBA-treated SAFB1+/+ and SAFB1+/-mice." (PMID 19267898, 2009). "Consistent with these recent findings, we have shown that Wnt-1 protein is over-expressed in HCC tissues and cell lines, but not in adjacent non-tumor liver tissues or cultured normal hepatocytes." (PMID 19778454, 2009). "Then, to determine whether CWP232228 treatment affects Wnt/β-catenin signaling in vivo, we investigated the expression patterns of its signaling components, Wnt1, LEF1, and β-catenin in tumor tissues of mice with or without CWP232228 treatment." (PMID 26967248, 2016). "The tumor formation speed in both cohorts of mice is markedly faster than that in AAV-P– and Lenti-PIK3CAH1047R–infected mice without the MMTV-Wnt1 transgene or in MMTV-Wnt1 mice without viral injection, demonstrating that PI3K and Wnt1 collaborate to promote mammary tumorigenesis." (PMID 37172086, 2023).
cancer (169 papers, 2004 to 2026). A tumor composed of atypical neoplastic, often pleomorphic cells that invade other tissues. "Both in vitro and in vivo studies have shown that salmonella can reduce Wnt-1 levels in intestinal epithelial cells, and the downregulation of Wnt-1 levels in cancer cells is associated with cancer progression." (PMID 37020597, 2023). "Owing to its key regulatory roles in development and homeostasis, Wnt signaling has been linked to cancer since the discovery that activation of int1 (Wnt1) resulted in mammary hyperplasia and tumors." (PMID 37699867, 2023). "Second, the associations between cancer grade and WNT-1 and mTOR expression are supported by immunohistochemical findings." (PMID 37176048, 2023). "Literature studies have also shown that the malfunction of Wnt1 is associated with various cancers, genetic type XV osteogenesis imperfecta, osteoporosis, and neurological diseases." (PMID 36056132, 2022). "WNT1 encodes a number of glycoproteins that are reported to be markers of advanced metastasis in cancer patients." (PMID 31850854, 2019). "Molecularly, the observed inclination towards the cancer stem-like properties was associated with the increased expression level of Notch1, WNT1 (both markers of stemness), NF-κB and Vimentin." (PMID 30005681, 2018). "We now know c-Myc is downstream of the Wnt targetome, but it was the discovery of Wnt1 itself that was exciting to many in the scientific community as it linked Drosophila embryogenesis and the Wingless protein to protooncogenes and cancer." (PMID 28373885, 2017). "In fact, an autophagy-independent role for Beclin 1 loss was reported to contribute to the enhanced cancer stem cell maintenance and tumorigenesis that was observed in WNT1/BECN1+/−mice." (PMID 28881721, 2017). "The Wnt-1/Frizzled protein receptor demonstrates that cell proliferation is associated with cancer cells." (PMID 23982808, 2013). "Mutations in Wnt1 are reported to be associated with various cancers and other human diseases." (PMID 36056132, 2022). "The WNT1 signaling pathway is known to play an important role in regulating the activation of cancer-associated fibroblasts, and this may explain the regulatory effect of miR-34c on activation of fibroblasts." (PMID 34261453, 2021). "Some studies reported a relationship between metastasis-associated protein 1 (MTA1) and the regulation of Wnt1 in endothelial and cancer cells, and MTA1 might be a novel target for leptin." (PMID 31736756, 2019). "However, squamous metaplasia was also identified in some MMTV-associated (7 of 9) and Wnt1-induced (12 of 13) type P tumors, Myc-induced carcinomas (7 of 19), adenomyoepitheliomas (3 of 5), and spontaneous carcinomas exhibiting EMT (1 of 4)." (PMID 15535849, 2004). "In the cancer pathway, five genes (WNT1, DLL, TRAF1, GST, and GADD45) were upregulated, while CASP3, IKBKA, STAT5A, RPS6KA5, BIRC5, BIRC2/3, and SKP2 were downregulated." (PMID 40723320, 2025). "Wnt1 can regulate cancer progression by promoting cancer cell proliferation, migration, and survival." (PMID 38388484, 2024). "β catenin, one of the cancer malignancy markers in the Wnt1 pathway, showed the most drastic changes in this regard." (PMID 39273283, 2024). "Expressions of Wnt1, β‐catenin and cyclin D1 at the protein level in NSCLC cells increased the risk of mutagenesis, increased cancer cell viability and decreased apoptosis." (PMID 37697969, 2023). "For every 1% of cells expressing WNT-1 in the cytoplasm, the odds of the cancer grade being 3 were 274.9-times higher (OR = 274.9, 95% Cl = 5.1–14690.2, p = 0.006)." (PMID 37176048, 2023). "Accordingly, for every 1% of cells expressing WNT-1 in the plasma membrane, the odds of the cancer grade being 3 were 11-times lower (OR = 0.09, 95% Cl = 0.009–0.89, p = 0.04)." (PMID 37176048, 2023).
cancer (continued). "In the current study, it also became evident that, at the supramolecular level changes in collagen in cancer-invaded ECM, there was an association, direct or indirect, with WNT1, WNT3A, and WNT5A signaling." (PMID 36452484, 2022). "Wnt-1 is the first member of the Wnt family, which can promote cell proliferation and migration, prolong the survival time of cancer cells, and promote cancer progression." (PMID 35651810, 2022). "In cancer, low levels of miR-637 lead to up-regulation of Wnt1 in CRC and Wnt7 in GBM and activate the Wnt/β-catenin pathway, thereby promoting cancer cell invasion, metastasis, metabolism, and inflammation." (PMID 36175921, 2022). "Among these genes, we focused on WNT1, which is involved in the canonical Wnt signaling pathway (also known as Wnt/β-Catenin) in cancer cells." (PMID 36393855, 2022). "Surprisingly, cancer-related pathways were significantly associated with intramuscular fat tissue, including TGF-β, Wnt-1, Ras, and Rho signaling-related genes." (PMID 34440281, 2021). "WNT1 is the initiating factor of the canonical Wnt/β-catenin signaling pathway and is highly expressed in many malignant tumors." (PMID 32898953, 2021). "Further, we observed that expression of WNT1 was upregulated in CCC-HSF-1 cells treated with exosomes from cancer cells, and downregulated in miR-34c-loaded exosomes at both the mRNA and protein levels." (PMID 34261453, 2021). "Studies have demonstrated that the overexpression of WNT1 gene in the Wnt signaling pathway can induce the apoptotic resistance of cancer cells." (PMID 32849930, 2020). "Accordingly, CCL2 secretion by breast tumor cells activated Wnt-1 production by mammary intra-epithelial macrophages inducing an epithelial/mesenchymal transition-like signaling on cancer cells and driving early cancer dissemination." (PMID 31417566, 2019). "Wnt1 silencing slightly decreased b-catenin activation and impaired cancer cell proliferation, indicating that Wnt1 is required for cell-autonomous growth." (PMID 30926812, 2019). "Studies have shown changes in the expression of MUTYH, KLF6, KLF4 and WNT1 genes in various cancers." (PMID 31724937, 2019). "Unbiased analysis of the Cancer Genome Atlas (TCGA) transcriptomics database shows that amongst all human Wnts, Wnt1 correlates positively with the expression of tolerogenic genes across the vast majority of cancers, including LUAD." (PMID 30926812, 2019). "Wnt1 is present within the exosomes of CAGE-expressing cancer cells and we show that exosomes and Wnt1 mediate these cellular interactions." (PMID 31799196, 2019). "Accordingly, in vivo RNA interference against Wnt1 not only impacted cancer cell autonomous proliferation but also rescued cDCs from b-catenin activation, leading to retardation of lung tumor growth." (PMID 30926812, 2019). "Recent studies have shown that the increased expression of WNT1 has occurred in many cancers, including breast, colon lung and prostate cancers, which, through inhibition of antagonists, have an oncogene role." (PMID 31724937, 2019). "To substantiate further Wnt1 paracrine signaling in cDCs, we exposed splenic cDCs in culture supernatants of several Wnt1 overexpressing cancer cells vs. those of control cells." (PMID 30926812, 2019). "On the other hand, antagonist monoclonal antibodies against the Wnt ligands Wnt1 and Wnt2 have provided beneficial results in various cancers, including NSCLC." (PMID 31608072, 2019). "Polyethylene glycol-polyethyleneimine-chlorin e6 (PEG-PEI-Ce6) nanoparticles delivered Wnt-1 siRNA to the cytoplasm of KB cells enhanced the cancer cell-killing effect by photodynamic therapy (PDT)." (PMID 31744202, 2019). "Here the authors show that intra-epithelial macrophages in the early pre-cancer lesions drive early cancer cell dissemination through Wnt-1 secretion and that such events impact the later development of metastasis." (PMID 29295986, 2018).
cancer (continued). "Mechanistically, we show that, in pre-malignant lesions, CCL2 produced by cancer cells and myeloid cells attracts CD206+/Tie2+ macrophages and induces Wnt-1 upregulation that in turn downregulates E-cadherin junctions in the HER2+ early cancer cells." (PMID 29295986, 2018). "Several studies have shown that MTA1 acts as an important upstream modifier of Wnt1 signaling in cancer cells." (PMID 29334999, 2018). "Our data suggest that intra-epithelial macrophages respond to CCL2, which in turn can stimulate macrophages to produce Wnt-1, leading to disruption of E-cadherin junctions between early cancer cells." (PMID 29295986, 2018). "Our data showed that the Wnt1 expression was negatively correlated with the expression of miRNA-148a in both primary cancer tissues and their corresponding adjacent normal lung tissues." (PMID 28199399, 2017). "The expression of SEAP in H1299 cells harboring these reporters were used as the criterion to evaluate if the 6-substituted 9-chloro-11H-indeno[1,2-c]quinolin-11-one derivatives repressed the expression of WNT1 in cancer cells." (PMID 27626678, 2016). "Since the Wnt1-mediated signaling pathway was shown to have an important role in cancer migration and invasion, the cellular effects of suppressing WNT1 expression by SJ26 were analyzed." (PMID 27626678, 2016). "Significantly, the Wnt1-mediated signaling pathway can be repressed upon the addition of G-quadruplex stabilizing agents in cancer cells." (PMID 27626678, 2016). "SJ26 effectively represses the expression of WNT1, its downstream signaling pathway, and the migration activity of cancer cells." (PMID 27626678, 2016). "Previous studies have demonstrated that down-regulation of the Wnt/β-catenin or Wnt-1 pathway by small interfering RNAs (siRNA) or Wnt-1-targeted monoclonal antibodies induces apoptosis in a variety of human cancer cells." (PMID 26968952, 2016). "In a mouse model of spontaneous tumorigenesis caused by WNT1 overexpression, the luminal epithelial progenitor marker ITGB3 identified a highly tumorigenic cancer stem cell population." (PMID 27833078, 2016). "As expected, hypoxic exposure significantly increased cancer stemness related factors (c-Myc, Klf4, Nanog, and Oct4) and Wnt/β-catenin signaling components (Wnt1, TCF4, and Cyclin D1)." (PMID 26965643, 2016). "Nevertheless, the correlation between Wnt1/β-catenin repressing and migration inhibition by SJ26 provides strong indication that SJ26 inhibit the migration activity of cancer cells through repressing the expression of WNT1." (PMID 27626678, 2016). "We found that compound SJ26 showed potent inhibitory effects to the Wnt1-mediated downstream signaling pathway in a G-quadruplex structure dependent manner and inhibited the migration activity of cancer cells." (PMID 27626678, 2016). "It has been reported that Wnt1 is up-regulated in several types of human cancer, including HCV-related HCC." (PMID 24416131, 2014). "STAT5 is present, along with phosphorylated PR, on the regulatory region of WNT1, a key Ser81 target gene known to be involved in cancer and stem cell biology." (PMID 24552158, 2014). "Wnt1 and Wnt2 were overexpressed in NSCLC samples and cancer cells, with Wnt1 expression exhibiting resistance to apoptosis-inducing therapy." (PMID 24260047, 2013). "A monoclonal antibody against Wnt-1 has shown to induce apoptosis in cancer cell lines expressing the Wnt-1 protein." (PMID 23016862, 2013). "The overexpression of Wnt1 was reported in various human cancers and is also suggested to be involved in ccRCC progression, as observed in Wnt ligand screening in RCC cancer samples." (PMID 23708097, 2013). "It was suggested that cancers driven by WNT-1 signaling would likely be enhanced by SULF1, whereas others, where FGF2 or HGF signaling is the more significant driving mechanism, are inhibited." (PMID 23144729, 2012).